USP20 (ubiquitin specific peptidase 20)
Description:
Deubiquitinating enzyme that plays a role in many cellular processes including autophagy, cellular antiviral response or membrane protein biogenesis. Attenuates TLR4-mediated NF-kappa-B signaling by cooperating with beta-arrestin-2/ARRB2 and inhibiting TRAF6 autoubiquitination. Promotes cellular antiviral responses by deconjugating 'Lys-33' and 'Lys-48'-linked ubiquitination of STING1 leading to its stabilization. Plays an essential role in autophagy induction by regulating the ULK1 stability through deubiquitination of ULK1. Acts as a positive regulator for NF-kappa-B activation by TNF through deubiquitinating 'Lys-48'-linked polyubiquitination of SQSTM1, leading to its increased stability. Acts as a regulator of G protein-coupled receptor (GPCR) signaling by mediating the deubiquitination beta-2 adrenergic receptor (ADRB2). Plays a central role in ADRB2 recycling and resensitization after prolonged agonist stimulation by constitutively binding ADRB2, mediating deubiquitination of ADRB2 and inhibiting lysosomal trafficking of ADRB2. Upon dissociation, it is probably transferred to the translocated beta-arrestins, possibly leading to beta-arrestins deubiquitination and disengagement from ADRB2. This suggests the existence of a dynamic exchange between the ADRB2 and beta-arrestins. Deubiquitinates DIO2, thereby regulating thyroid hormone regulation. Deubiquitinates HIF1A, leading to stabilize HIF1A and enhance HIF1A-mediated activity. Deubiquitinates MCL1, a pivotal member of the anti-apoptotic Bcl-2 protein family to regulate its stability. Within the endoplasmic reticulum, participates with USP33 in the rescue of post-translationally targeted membrane proteins that are inappropriately ubiquitinated by the cytosolic protein quality control in the cytosol.
Synonyms: hVDU2; KIAA1003; LSFR3A; VDU2
Tractability: Antibody: the Human Protein Atlas places it where antibodies can reach. PROTAC: UniProt records ubiquitination sites on it; ubiquitination databases record sites on it; its protein half-life has been measured.
Target class: Cysteine protease; Cysteine protease CA clan; Protease; Enzyme; Cysteine protease C19 family
Gene: Protein-coding gene on chromosome 9 (129,834,698 to 129,881,842, forward strand). Ensembl gene ENSG00000136878.
Subcellular location: Cytoplasm; Endoplasmic reticulum; Cytoplasm, perinuclear region; Cytoplasm, cytoskeleton, microtubule organizing center, centrosome
Subcellular location (Human Protein Atlas): Cytosol; Nucleoplasm; Plasma membrane
Pathways (Reactome):
Metabolism of proteins: Ub-specific processing proteases
Gene Ontology:
Molecular function: cysteine-type deubiquitinase activity; cysteine-type endopeptidase activity; G protein-coupled receptor binding; protein binding; zinc ion binding
Biological process: antiviral innate immune response; negative regulation of canonical NF-kappaB signal transduction; positive regulation of autophagy; protein deubiquitination; protein K48-linked deubiquitination; protein K63-linked deubiquitination; regulation of G protein-coupled receptor signaling pathway; nervous system development
Cellular component: centrosome; endoplasmic reticulum; cytoplasm; cytosol; perinuclear region of cytoplasm
Genetic constraint (gnomAD): Loss-of-function variants: 80 observed, 122.88 expected, observed/expected ratio (o/e) 0.65, 90% interval 0.54 to 0.78. The upper end of that interval is the gene's LOEUF score, 0.78, which puts it in group 3 of 6, group 1 being the genes least tolerant of losing a copy. Missense variants: 1,042 observed, 1,253.3 expected, observed/expected ratio (o/e) 0.83, 90% interval 0.79 to 0.88. Synonymous variants: 481 observed, 519.38 expected, observed/expected ratio (o/e) 0.93, 90% interval 0.86 to 1.
Homologues: Orthologues: chimpanzee USP20 (99% identical), macaque USP20 (99% identical), dog USP20 (94% identical), pig USP20 (94% identical), mouse Usp20 (93% identical), rat Usp20 (92% identical), rabbit USP20 (89% identical), guinea pig USP20 (87% identical), tropical clawed frog usp20 (77% identical), zebrafish usp20 (76% identical). Paralogues in human: USP33 (60% identical), USP44 (19% identical), USP49 (19% identical), USP9X (18% identical), USP9Y (17% identical), USP24 (17% identical), USP15 (16% identical), USP11 (16% identical), USP3 (16% identical), USP4 (16% identical), USP19 (16% identical), USP32 (16% identical), and 59 more.
Diseases named in the same sentence as USP20 in open-access papers:
USP20 is named in the same sentence as 45 diseases in open-access papers, as found by Europe PMC text mining. Sharing a sentence is not in itself a finding about the gene and the disease. The quoted sentences say what the papers report.
breast carcinoma (7 papers, 2021 to 2025). "Emerging studies have revealed the pivotal role of USP20 in the tumorigenesis of various cancer types, such as breast cancer, colon cancer, lung cancer, gastric cancer and adult T cell leukemia." (PMID 35508480, 2022). "In an in vitro study, they found that knockdown of USP20 can suppress the lung colonization of breast cancer cell lines." (PMID 35508480, 2022). "Among the mechanisms by which USP20 affects the migration of breast cancer cell lines, they demonstrated that USP20 was correlated with ERK3, and the stability of ERK3 protein was increased by USP20." (PMID 35508480, 2022). "USP20 positively correlates with SNAI2 in breast cancer patients and a high level of USP20 is suggestive of adverse outcomes in ER- breast cancers." (PMID 34575114, 2021). "In addition, USP20 can promote breast cancer metastasis by stabilizing SNAI2." (PMID 36463222, 2022). "It has previously been reported that, upon its stabilisation by USP20, ERK3 decreases cell–ECM adhesion and promotes migration of various breast cancer cell lines." (PMID 40936697, 2025). "Meanwhile, they detected USP20 and SNAI2 in ER– clinical breast cancer samples, and demonstrated that USP20 positively correlated with SNAI2." (PMID 35508480, 2022). "First, their studies showed that both USP20 and ERK3 are overexpressed in multiple breast cancer cell lines, including MCF7, T47D, and SKBR3." (PMID 35508480, 2022). "Higher protein level of USP20 and SNAI2 was also demonstrated to predict worse prognosis in ER– breast cancer patients." (PMID 35508480, 2022). "They demonstrated that USP20 overexpression could enhance HeLa cell migration, and they further examined the impact of the USP20-ERK3 axis in regulating the migration of breast cancer cell lines." (PMID 35508480, 2022). "In examining the upstream regulatory mechanism of TINCR in breast cancer, we found that IFN-γ stimulation can activate downstream STAT1 signaling and that STAT1 migrates to the nucleus to promote the transcription of TINCR, thus regulating the expression of downstream miR-199a-5p, USP20, and PD-L1." (PMID 36725842, 2023).
atherosclerosis (5 papers, 2023 to 2025). A disease characterized by the build-up of fatty material and calcium deposition in the arterial wall resulting in partial or complete occlusion of the arterial lumen. "Genetic and pharmacologic interventions that mitigate neointimal hyperplasia almost always mitigate atherosclerosis—as we and others have shown, including with USP20 itself." (PMID 37311534, 2023). "Ubiquitin-specific peptidase 20 (USP20) reduces NFκB activation triggered by proinflammatory stimuli, and USP20 activity attenuates atherosclerosis in mice." (PMID 37311534, 2023). "Regarding atherosclerosis, USP20 in smooth muscle cells has a restorative role characterized by the modulation of inflammatory signals, but it increases risk by promoting cholesterol synthesis in the liver." (PMID 36834633, 2023). "Considering that vascular inflammation contributes to the pathogenesis of atherosclerosis, USP20 in smooth muscle cells is likely to attenuate the incidence of atherosclerosis." (PMID 36834633, 2023). "Considering the pathogenetic roles of LDL, hepatic USP20 might contribute to the exacerbation of atherosclerosis." (PMID 36834633, 2023). "Thus, USP20 in vascular smooth muscle cells mitigates atherosclerosis by repressing NF-κB-evoked inflammatory responses." (PMID 36834633, 2023). "Thus, arterial inflammation inherent in atherosclerosis correlates with phosphorylation of USP20 on its regulatory residue Ser333." (PMID 37311534, 2023). "Whether targeting USP20-Ser334 phosphorylation therapeutically could mitigate inflammatory vascular diseases like atherosclerosis remains an intriguing possibility." (PMID 37311534, 2023). "We conclude that USP20 expression inversely correlates with the extent of angiogenesis, and that inhibiting USP20 Ser334 phosphorylation could be a useful strategy to constrain inflammation-driven angiogenesis under pathological circumstances, like cancer and atherosclerosis." (PMID 40475497, 2025). "To discern whether USP20 Ser333 phosphorylation could be relevant in human atherosclerosis, we used IgG specific for phospho-USP20(Ser333) to immunostain atherosclerotic human arteries obtained from legs that had been amputated because of arterial insufficiency." (PMID 37311534, 2023). "The deubiquitinase ubiquitin-specific peptidase 20 (USP20) suppresses NFκB activation in vascular smooth muscle cells (SMCs) and attenuates atherosclerosis, but the role of USP20 in endothelial cells (ECs) was undefined." (PMID 40475497, 2025). "In conclusion, inhibition of Usp20 by an LNP–siRNA complex can alleviate hyperlipidemia and prevent atherosclerosis." (PMID 39173829, 2024). "The results showed that silencing Usp20 by LNP-siRNA reduced lipid contents in serum, decreased body weight, and prevented atherosclerosis." (PMID 39173829, 2024). "Likewise, USP20 in hepatocytes and USP14 in smooth muscle cells exacerbate atherosclerosis, whereas USP20 in smooth muscle cells and USP14 in endothelial cells improve disease outcomes." (PMID 36834633, 2023).
gastric cancer (4 papers, 2019 to 2025). A primary or metastatic malignant neoplasm involving the stomach. "Further, it has been shown that claspin expression in gastric cancer samples correlates with USP20 expression and that low claspin and USP20 levels are associated with worse overall survival." (PMID 31208103, 2019). "In contrast, high Claspin and USP20 expression were correlated with enhanced overall survival, pointing to a protective role for Claspin and USP20 in gastric cancer." (PMID 41009395, 2025). "Due to its ability to inhibit the malignant characteristics of gastric cancer cells via the positive regulation of claspin, USP20 is considered to play a tumor-suppressing role in gastric cancer." (PMID 31208103, 2019). "It prompted us to speculate that USP20 is a promising new molecular target to design new therapeutic modalities to control the development and progression of gastric cancer." (PMID 35508480, 2022). "In gastric cancer (GC), DUBs like USP20, OTUB1, and OTUD1 play significant roles." (PMID 39678489, 2024). "Although USP20 serves as an oncogene in varied cancer types, it also acts as a tumor suppressor in a few cancer types, including ATL and gastric cancer." (PMID 35508480, 2022).
hepatocellular carcinoma (4 papers, 2023 to 2025). A malignant tumor that arises from hepatocytes. "Thus, high expression of USP20 is associated with poor prognosis in hepatocellular carcinoma and contributes to oxaliplatin and ferroptosis resistance of hepatocellular carcinoma cells." (PMID 39624080, 2024). "Ubiquitin-specific peptidase 20 (USP20) inhibits ferroptosis in OxA-resistant hepatocellular carcinoma (HCC) cells." (PMID 40959280, 2025). "USP20 is a key factor in the interaction between oxaliplatin (OXA) resistance and ferroptosis in hepatocellular carcinoma." (PMID 38124786, 2023).
colon cancer (3 papers, 2014 to 2022). "They demonstrated that USP20 expression was positively correlated with the β-catenin levels in clinical colon cancer samples." (PMID 35508480, 2022). "To verify this possibility, we generated a USP20-depleted HT29 colon cancer cell line by infection of lentiviruses expressing USP20-specific shRNA." (PMID 32354117, 2020). "Furthermore, in a mouse xenograft tumor model, colon cancer HCT116 cells stably depleted of USP20 expression by lentiviral shRNA, when transplanted onto nude mice, developed significantly larger tumor volumes than mock-depleted HCT116 cells." (PMID 25326330, 2014).
colorectal cancer (3 papers, 2022 to 2023). A primary or metastatic malignant neoplasm that affects the colon or rectum. "In colorectal cancer, USP20 has been reported to deubiquitinate and stabilize β-catenin, which in turn promotes cancer cell growth, invasion and chemoresistance." (PMID 37726816, 2023). "We therefore hypothesize that USP20 regulates the NOTCH pathway, HEDGEHOG pathway, BETA CATENIN pathway through affecting mRNA modification and transport, thereby promoting metastasis and chemoresistance in colorectal cancer." (PMID 36874086, 2023).
Obesity (3 papers, 2022 to 2024). Accumulation of substantial excess body fat. "As mentioned in Section 2, obesity induced by a 23-week high-fat and high-sucrose diet was mitigated in liver-specific Usp20KO mice, indicating that liver-specific Usp20 deficiency caused significant restoration of glucose and insulin tolerance." (PMID 36834633, 2023). "Several studies have utilized chemical blockers to assess the roles of USP in metabolic disorders; e.g., GSK2643953A for USP20 in obesity, ML323 and SJB-043 for USP1 in β-cell damage, ML364 for USP2 in hypothalamic function, and HBX41108 for USP7 in diabetic foot ulcers." (PMID 36834633, 2023). "In order to explore whether USP20 can be used as a therapeutic target for metabolic diseases such as obesity, investigators gave USP20 inhibitor to obese mice." (PMID 35754818, 2022). "After injection of si-Usp20, the level of HMGCR protein was decreased to ∼50%, and the fatty acid synthesis pathway was downregulated in obesity resulting from a HFD." (PMID 39173829, 2024).
von Hippel-Lindau disease (3 papers, 2008 to 2024). An autosomal dominant disorder caused by pathogenic variants in the VHL gene, leading to an increased risk of various benign and malignant tumors, including hemangioblastomas, retinal hemangiomas, endolymphatic sac tumors, renal cell carcinoma, and pheochromocytomas. "Studies have indicated that the pathophysiology of Von Hippel-Lindau Syndrome (VHL) is linked to USP20 and USP33." (PMID 38613804, 2024). "USP20, also known as von Hippel–Lindau (pVHL)-interacting deubiquitinating enzyme 2 (VDU2), was initially identified as a deubiquitinase associated with von Hippel–Lindau (VHL) syndrome." (PMID 38474186, 2024). "UBP33 (encoded by USP33/VDU1) and UBP20 (encoded by USP20/VDU2) are 59% identical USP-type DUBs that interact with the tumor suppressor E3 ubiquitin ligase VHL (pVHL), mutations in which are associated with von Hippel-Lindau disease." (PMID 19007433, 2008).
lymph node metastasis (2 papers, 2023 to 2025). "Additional analyses in TCGA samples and our cohort showed that USP20 was associated with lymph node metastasis in patients with CRC." (PMID 36874086, 2023). "Our results suggest that high USP20 expression is closely associated with lymph node metastasis in CRC patients." (PMID 36874086, 2023). "High USP20 expression was shown to be associated with lymph node metastasis (P<0.001) and American Joint Committee on Cancer (AJCC) stage (P<0.001)." (PMID 36874086, 2023). "Correlation analysis showed that USP20 expression was associated with lymph node metastasis." (PMID 36874086, 2023). "Analysis of TCGA datasets showed that the expression of USP20 and CTSL progressively increased with the extent of lymph node metastasis (N stage), further supporting their association with metastatic potential." (PMID 41261048, 2025). "Moreover, USP20 overexpression was positively correlated with lymph node metastasis and advanced AJCC stage." (PMID 41261048, 2025).
Angelman syndrome (1 paper, 2024). A neurogenetic disorder characterized by severe intellectual deficit and distinct facial dysmorphic features. "Taking into account all the evidence presented in this study, it suggests that targeting USP20 and/or ULK1 could potentially hold therapeutic promise for individuals affected by HERC2-related disorder and Angelman syndrome." (PMID 38570483, 2024).
aortic atherosclerosis (1 paper, 2023). A atherosclerosis that involves the aorta.
bladder cancer (1 paper, 2025). "Recent studies have further revealed that USP20 can promote bladder cancer progression by regulating the Hippo‐YAP1 signalling pathway." (PMID 41261048, 2025).
breast tumor (1 paper, 2023). "USP20 was shown to promote breast tumor metastasis, and proliferation of oral squamous carcinoma cells." (PMID 36874086, 2023).